ATP13A2 (ATPase cation transporting 13A2)
Diseases named in the same sentence as ATP13A2 in open-access papers (continued):
Sharing a sentence is not in itself a finding about the gene and the disease.
colon cancer (7 papers, 2020 to 2025). "ATP13A2 has been implicated in melanoma, colon cancer, hepatocellular carcinoma, acute myeloid leukemia and non‐small‐cell lung cancer." (PMID 39981745, 2025). "The PD-associated gene ATP13A2 is involved in colon cancer stemness through regulation of autophagy." (PMID 33308286, 2020). "Indeed, ATP13A2 has been implicated in several human cancers, including melanoma, colon cancer, hepatocellular carcinoma, acute myeloid leukemia and non-small-cell lung cancer, while ATP13A3 has been linked to pancreatic cancer and colorectal cancer." (PMID 37371498, 2023). "While all of these pieces of evidence point to ATP13A2 and autophagy, studies have also revealed a link between the level of ATP13A2 expression and the survival rate of colon cancer patients." (PMID 35884586, 2022). "Colon cancer patients with elevated ATP13A2 expression displayed shorter overall survival than those with low ATP13A2." (PMID 35884586, 2022). "In this study, to the best of our knowledge, we report for the first time that ATP13A2 functions in the promotion of colon cancer stemness and is a predictive factor of colon cancer patient outcomes." (PMID 33308286, 2020). "Immunohistochemical analyses also showed that the numbers of ATP13A2-, LC3-, and cancer stem cell-positive cells were lower in the siATP13A2-injected tumors, indicating that ATP13A2 was involved in sustaining the stemness of colon cancer via autophagy in vivo." (PMID 33308286, 2020). "Taken together, these results suggest that ATP13A2 contributes to colon cancer stemness through regulation of the autophagic process." (PMID 33308286, 2020). "The findings of this study illustrate the role of ATP13A2 in colon cancer and show that ATP13A2 is a putative novel prognostic marker as well as a novel potential therapeutic target in colon cancer." (PMID 33308286, 2020). "Meanwhile, overexpression of ATP13A2 increased the number of colonies formed by the colon cancer cells compared to those formed by the mock cells." (PMID 33308286, 2020). "We next analyzed the association of ATP13A2 expression with the lifespan and tumor-node-metastasis (TNM) stage of colon cancer patients using the clinicopathological features of the patients." (PMID 33308286, 2020). "The localization of ATP13A2 within the lysosomal membrane implies that it plays a role in modulating autophagy; therefore, we analyzed human colon cancer specimens." (PMID 33308286, 2020). "We found that the expression of was higher the autophagy marker (LC3 and SQSTM1) in ATP13A2 low colon cancer cells, but lower in ATP13A2 high colon cancer cells." (PMID 33308286, 2020). "More importantly, the level of ATP13A2 expression in colon cancer was positively correlated with lymph node metastasis (P = 0.019)." (PMID 33308286, 2020). "IHC using a 99-case colon cancer cohort (Cohort-99) revealed that in 80 paired cases, the staining score of ATP13A2 was remarkably higher in the tumor tissue than in the corresponding adjacent non-cancerous tissue." (PMID 33308286, 2020). "We also aimed to understand the role of ATP13A2 in maintaining the colon cancer invasive capacity and stemness." (PMID 33308286, 2020). "We performed a series of ATP13A2 knockdown and overexpression studies in vitro to identify the contribution of ATP13A2 in the stemness and invasive capacity of colon cancer cells." (PMID 33308286, 2020). "We next investigated the relationship between ATP13A2 expression and the invasive capacity of colon cancer cells." (PMID 33308286, 2020). "The results showed that ATP13A2 expression levels were higher in advanced stages than those in early stages of colon cancer." (PMID 33308286, 2020). "IHC staining was performed on the 99-case colon cancer cohort to explore the relationship between the expression levels of ATP13A2, LC3 and SQSTM1, the marker of autophagy." (PMID 33308286, 2020).
colon cancer (continued). "Taken together, these data suggest that ATP13A2 knockdown blocks autophagic flux, resulting in reduced stemness of colon cancer cells." (PMID 33308286, 2020). "Colon cancer patients with high ATP13A2 expression exhibit shorter overall survival than those with low ATP13A2." (PMID 33308286, 2020). "Our studies also showed that knockdown of ATP13A2 in colon cancer cells decreased the self-renewal ability of cells, and this capability was rescued by ATP13A2 overexpression." (PMID 33308286, 2020). "We have also demonstrated that the knockdown of ATP13A2 abolished the stemness of cancer cells in vitro and that targeting ATP13A2 in colon cancer cells decreased the volume of the tumor xenograft in vivo." (PMID 33308286, 2020). "Further investigation showed that ATP13A2 regulates the stemness of colon cancer cells by regulating autophagy." (PMID 33308286, 2020). "Expectedly, the Transwell assay showed that decreased ATP13A2 level significantly impaired the mobility of colon cancer cells, while elevated ATP13A2 levels markedly enhanced their mobility." (PMID 33308286, 2020). "Taken together, these data indicated that ATP13A2 expression was significantly higher in colon cancer tissues than in adjacent colon tissues." (PMID 33308286, 2020). "Other research suggests that ATP13A2 may serve as a novel prognostic biomarker for colon cancer and a potential target for colon cancer therapy due to increased expression of ATP13A2 linking to shorter overall survival of colon cancer patients." (PMID 35252181, 2022). "Additionally, bafilomycin A1, an autophagy inhibitor, reversed the ATP13A2-induced stemness of colon cancer cells." (PMID 33308286, 2020). "We next correlated ATP13A2 expression with colon cancer prognosis." (PMID 33308286, 2020). "Therefore, it is worthwhile to explore the expression of ATP13A2 and autophagy in colon cancer cells." (PMID 33308286, 2020). "Lastly treatment with ATP13A2 siRNA reduced the volume of colon cancer xenografts in mice." (PMID 33308286, 2020). "Taken together, these findings suggest that ATP13A2 is involved in colon cancer initiation." (PMID 33308286, 2020). "Furthermore, the volume and number of tumor spheres derived from the siATP13A2-colon cancer cells were smaller than those derived from the siNC-colon cancer cells, and overexpression of ATP13A2 had reverse effects." (PMID 33308286, 2020). "Therefore, ATP13A2 expression in colon cancer appears to serve as a predictor for prognosis of colon cancer patients." (PMID 33308286, 2020). "Furthermore, univariate and multivariate analyses revealed that the expression of ATP13A2 is an independent indicator for the overall survival rate of patients with colon cancer." (PMID 33308286, 2020). "Therefore, we explored the potential relationship between ATP13A2 expression and stemness of colon cancers through knockdown and overexpression studies." (PMID 33308286, 2020). "As such, we conclude that targeting ATP13A2 in colon cancer may be a good strategy for killing cancer stem cells and for inhibiting non-cancer stem cells by blocking autophagic flux." (PMID 33308286, 2020). "Furthermore, ATP13A2 is a novel prognostic biomarker for colon cancer and is a potential target for colon cancer therapy." (PMID 33308286, 2020). "Additionally, ATP13A2 is not only a novel prognostic biomarker for colon cancer but also a potential target for colon cancer therapy." (PMID 33308286, 2020). "We next aimed to correlate ATP13A2 with colon cancer patient prognosis to determine whether it can be used as a prognostic predictor." (PMID 33308286, 2020). "In our previous study, we have revealed that PARK7 is associated with colon cancer invasion and progression, but the role of ATP13A2 in colon cancer initiation and progression remains unknown." (PMID 33308286, 2020). "Furthermore, we show that ATP13A2 can be considered as a therapeutic target in colon cancer." (PMID 33308286, 2020).
colon cancer (continued). "Finally, we knocked down ATP13A2 in mice using siRNA to determine whether it can be used as target for colon cancer treatment." (PMID 33308286, 2020). "Therefore, we investigated the role of ATP13A2 in autophagy regulation in colon cancer cells." (PMID 33308286, 2020). "We found that the mRNA levels of ATP13A2 and PARK7 were significantly higher in colon cancer tissue than in normal tissue." (PMID 33308286, 2020). "Finally, we tested whether ATP13A2 can be targeted in colon cancer therapy in mice." (PMID 33308286, 2020). "In addition, ATP13A2 mRNA expression from the ONCOMINE and GEPIA databases was noted to be higher in colon cancer tissues than in the normal tissues." (PMID 33308286, 2020). "However, HCT-116 cells treated with ATP13A2 targeting siRNA showed no increase in the number LC3-GFP puncta after bafilomycin A1 treatment; this was rescued by the overexpression of ATP13A2 in colon cancer cells, indicating that ATP13A2 knockdown decreased basal autophagic flux." (PMID 33308286, 2020).
Dystonia (6 papers, 2014 to 2023). An abnormally increased muscular tone that causes fixed abnormal postures. "Understanding ATP13A2 at the molecular level will reveal its link to KRS, NCL, dystonia, and PD." (PMID 24904274, 2014).
frontotemporal dementia (6 papers, 2013 to 2022). Frontotemporal dementia (FTD) comprises a group of neurodegenerative disorders, characterized by progressive changes in behavior, executive dysfunction and language impairment, as a result of degeneration of the medial prefrontal and frontoinsular cortices. "Instead, they were mostly referred to as frontotemporal lobar degeneration (caused by variants in the GRN/CLN11 gene) or a Parkinson-like neurodegenerative syndrome caused by variants in the ATP13A2/CLN12 gene." (PMID 36034292, 2022). "However, changes in several other genes have been suggested as causes for recessive neurological/neurodegenerative disorders that may include PD: hereditary ataxias (ATXN2/3, FMR1), frontotemporal dementia (e.g. MAPT) and others (e.g. ATP13A2, PLA2G6, FBXO7)." (PMID 23976986, 2013).
cognitive deficits (5 papers, 2019 to 2025). "In contrast, ATP13A2 Het mice develop a different phenotype that includes early cognitive deficits and age-related accumulation of αSyn in multiple brain regions." (PMID 40806164, 2025). "In addition to these pathologies, mutations in ATP13A2 have also been reported in a Bulgarian family with juvenile-onset hereditary spastic paraplegia (SPG78), characterized by a progressive pyramidal and cerebellar degeneration and cognitive deficits." (PMID 30992063, 2019). "ATP13A2-related NCL patients clinically present rigidity, akinesia and intellectual impairment." (PMID 31289639, 2019).
colorectal cancer (5 papers, 2023 to 2026). A primary or metastatic malignant neoplasm that affects the colon or rectum. "Dysfunction of the membrane transporter P5B-ATPase 13A2 (ATP13A2) has been linked to neurodegenerative disorders, while its overexpression has been associated with colorectal cancer." (PMID 41516358, 2026). "While the oncogene ATP13A2 is reportedly involved in colorectal cancer, its role in cervical cancer (CC) has yet to be fully characterized." (PMID 40197818, 2025). "Moreover, upregulation of ATP13A2 activates the pentose phosphate pathway to promote colorectal cancer growth." (PMID 41516358, 2026).
Lewy body disease (5 papers, 2013 to 2025). "Studies have shown that the over-expression of ATP13A2 reduces intracellular Mn concentration, which in turn, alleviates Mn-provoked lethality; loss-of-function mutations in ATP13A2 are correlated with increases in both α-synuclein and Aβ plaques in Lewy body disease." (PMID 29114205, 2017). "It remains unclear, however, whether accumulated α-synuclein causes reductions in ATP13A2 protein levels or if a decrease in functional ATP13A2 protein levels renders neurons vulnerable to α-synuclein toxicity in Lewy body diseases." (PMID 24252509, 2013). "There is overlap between the splicing event changes detected in the ATP13A2 mutant cell line and the altered transcript isoforms from Lewy body disease brain biopsy RNA-seq data." (PMID 40950074, 2025). "We have identified that ATP13A2 protein levels decrease and become more insoluble in association with increased levels and insolubility of α-synuclein in cases with Lewy body diseases, and confirm that ATP13A2 is colocalized in some Lewy bodies." (PMID 24252509, 2013). "In vitro data show that ATP13A2 deficits lead to lysosomal, autophagic and mitochondrial dysfunction and α-synuclein accumulation, which are known features of Lewy body diseases, and that increasing ATP13A2 levels can alleviate α-synuclein toxicity." (PMID 24252509, 2013). "In all Lewy body disease cases, we identified decreased ATP13A2 protein levels that correlated with increases in both α-synuclein and β-amyloid." (PMID 24252509, 2013). "In particular, the changes observed in ATP13A2 protein levels and localization in neurons containing α-synuclein pathology appear characteristic of Lewy body diseases." (PMID 24252509, 2013). "Our data show that patients with Lewy body diseases have an overall deficit in ATP13A2 protein levels, with the remaining protein being more insoluble and partially redistributing towards Lewy bodies." (PMID 24252509, 2013). "In idiopathic PD and Dementia with Lewy Bodies, ATP13A2 protein levels are significantly decreased postmortem, suggesting that altered ATP13A2 function may be more pervasive in phenotypic PD than previously considered." (PMID 40806164, 2025). "In idiopathic PD and Dementia with Lewy bodies, post mortem analysis shows ATP13A2 protein levels are significantly decreased suggesting altered ATP13A2 function may be more pervasive in phenotypic PD than previously thought." (PMID 38249738, 2023). "This supports the concept that increasing ATP13A2 levels may offer potential therapeutic benefits to patients with Lewy body diseases." (PMID 24252509, 2013). "Overall these data are supportive of the concept that increasing ATP13A2 levels may have potential therapeutic benefits in patients with Lewy body diseases." (PMID 24252509, 2013). "In this study, we sought to assess if ATP13A2 levels in Lewy body disease are modified by Alzheimer-type β-amyloid deposition by evaluating cases of pure PD that lack β-amyloid-positive plaques and pure dementia with Lewy bodies (DLB) and also β-amyloid-positive plaques." (PMID 24252509, 2013). "Comparison of immunoperoxidase localization of ATP13A2 in anterior cingulate cortex between PD and DLB cases and controls was performed, as a recent study suggested increased ATP13A2 protein expression in a Lewy body disease cohort that included both PD and DLB cases." (PMID 24252509, 2013). "To assess whether ATP13A2 levels in Lewy body disease are modified by Alzheimer-type β-amyloid deposition, we evaluated cases of pure PD and pure dementia with Lewy bodies (DLB) for changes in ATP13A2, α-synuclein and β-amyloid protein levels in cortical regions with and without Lewy bodies." (PMID 24252509, 2013).
synucleinopathies (5 papers, 2011 to 2025). "Heavy metal toxicity has been implicated in synucleinopathies, with a possible interaction of α-synuclein and copper, while the product of another PD gene, ATP13A2, may regulate cation homeostasis, and modulate cadmium toxicity." (PMID 31870437, 2019). "ATP13A2 plays an important role in the phosphorylation of pathologic α-synuclein in a Zn2+-induced α-synucleinopathy model." (PMID 35887392, 2022).
lysosomal storage disorder (4 papers, 2014 to 2019). "Mutations in ATP13A2 are associated with Kufor-Rakeb syndrome and young onset PD, as well as to the lysosomal storage disorder, neuronal ceroid lipofuscinosis." (PMID 31331333, 2019). "Also relevant to PD risk and lysosomal storage disorders, ATP13A2 is a lysosomal ATPase that acidifies the lysosomal lumen and therefore allows the lysosomal proteases to properly function." (PMID 31331333, 2019). "The fact that ATP13A2 is a lysosomal disorder means that there are tantalising links to lysosomal storage diseases." (PMID 25870938, 2016).
Onset (4 papers, 2017 to 2022). The age group in which disease manifestations appear. "Additionally, mutations in ATP13A2, also known as PARK9, which is a gene associated with autosomal recessive forms of early-onset PD, result in the dysregulation of Zn2+ homeostasis, thereby promoting lysosomal dysfunction and α-synuclein accumulation." (PMID 35887392, 2022). "In this respect, the human PARK9 (ATP13A2), a lysosomal type 5 P-type ATPase associated with autosomal recessive early-onset PD, has been shown to act as a transporter for lysosomal sequestration of cytoplasmic zinc." (PMID 33946908, 2021).
brain tumors (3 papers, 2016 to 2022). "Some PD genes, including PARK1/4, PINK1, and PARK9 (ATP13A2), have already been detected to be associated with brain tumors, indicating that the same mutations can lead to pathological changes in both PD and brain tumors." (PMID 33066407, 2020).
juvenile-onset Parkinson disease (3 papers, 2020 to 2026). "Loss-of-function (LOF) variants in ATP13A2 cause severe juvenile-onset Parkinson's disease, providing a window into the mechanisms that accelerate age-related neurodegeneration." (PMID 41993310, 2026). "ATP13A2 is a lysosomal polyamine transporter, mutated in several diseases including juvenile-onset Parkinson’s disease." (PMID 37031211, 2023).
Batten disease (2 papers, 2022 to 2024). "Commonly known as Batten disease, the different subtypes are each caused by a mutation in a distinct ceroid lipofuscinosis neuronal (CLN) gene (PPT1/CLN1, TPP1/CLN2, CLN3, DNAJC5/CLN4, CLN5, CLN6, MFSD8/CLN7, CLN8, CTSD/CLN10, PGRN/CLN11, ATP13A2/CLN12, CTSF/CLN13)." (PMID 35252181, 2022).
breast carcinoma (2 papers, 2023 to 2026). "Follow-up studies are required to investigate whether increased ATP13A4 expression is a general hallmark of breast cancer, or whether other polyamine transporters such as ATP13A2 and ATP13A3 may also be implicated." (PMID 37371498, 2023). "In contrast to the ubiquitously expressed ATP13A2-3 isoforms, ATP13A4 expression is tissue-specific and found mainly in epithelial glandular tissue such as the mammary glands, which fits well with a putative role in breast cancer." (PMID 37371498, 2023).
developmental delay (2 papers, 2024 to 2025). "These neurodevelopmental features allowed us to better understand the early life of Atp13a2 KO rats, showing mild developmental delays with a critical locomotor period." (PMID 41253848, 2025).
epilepsy (2 papers, 2023 to 2024). A brain disorder characterized by episodes of abnormally increased neuronal discharge resulting in transient episodes of sensory or motor neurological dysfunction, or psychic dysfunction. "Using WES, homozygous pathogenic variants in the COL18A1, UFSP2, ZFYVE26 and ATP13A2 genes were detected to cause ASM-resistant epilepsy and its comorbid conditions in four Pakistani families." (PMID 38783254, 2024). "Consequently, our study strongly supports the hypothesis that the ATP13A2 variant is causative for ASM-resistant epilepsy and the associated comorbidities, including PD." (PMID 38783254, 2024). "In the current study, we identified a homozygous missense variant in the ATP13A2 gene, specifically c.1208 C > A, p.Ala403Glu, in a family displaying a range of symptoms, including ASM-resistant epilepsy, ID, DD, PD, deafness, drooling, speech impediments, hypotonia, and a weak cry." (PMID 38783254, 2024).
Juvenile onset (2 papers, 2013 to 2019). Onset of signs or symptoms of disease between the age of 5 and 15 years. "From a population genetics standpoint, we were able to provide further credence for the causality of ATP13A2 in juvenile-onset ALS, by identifying a second individual with recessive truncating alleles in this gene." (PMID 30992063, 2019). "We next parsed all candidates against a cohort of 3641 ALS cases; only ATP13A2 was found to harbor recessive changes, in a patient with juvenile-onset ALS, similar to the index case." (PMID 30992063, 2019).